KIT (KIT proto-oncogene, receptor tyrosine kinase)
Diseases named in the same sentence as KIT in open-access papers (continued):
Sharing a sentence is not in itself a finding about the gene and the disease.
seminoma (89 papers, 2007 to 2026). A radiosensitive malignant germ cell tumor found in the testis (especially undescended), and extragonadal sites (anterior mediastinum and pineal gland). "The most frequently mutated GCT gene is KIT, in which activating mutations are observed in 25–30% of seminomas." (PMID 40358182, 2025). "Four KIT alterations were identified, with one seminoma (TGCT-7) having a co-existing missense mutation and a copy number gain." (PMID 41009531, 2025). "KIT mutations are also found in approximately one-third of teratomas or seminomas, indicating that KIT signaling plays a key role in the development of germ cell tumors." (PMID 41568380, 2025). "Our analysis did not reveal a single distinct mutation or hotspot specific to seminoma, consistent with previous studies that highlight a polygenic model with KIT and KRAS as frequent drivers." (PMID 41154418, 2025). "A total of 42.9% (3/7) of seminomas had a KIT mutation, with missense gain-of-function variants detected in three tumors (TGCT-2, TGCT-6, and TGCT-7)." (PMID 41009531, 2025). "In patient SP2, the KIT mutation was concordant in the right and left synchronous seminomas, while in patient SP7, the KRAS mutation was concordant in the right and left synchronous seminomas." (PMID 40358182, 2025). "In contrast, only three non-seminoma tumors showed evidence of pre-WGD driver mutations (three KIT and one RAC1)." (PMID 40568177, 2025). "In summary, analysis of AACR Project GENIE data sheds light on a distinct seminoma genomic profile characterized by recurrent mutations in KIT, KRAS, and MTOR, as well as focal copy number alterations in CDKN1B, KRAS, CCND2, and H3F3C." (PMID 41154418, 2025). "Though the occurrence of somatic KIT mutations is primarily observed in seminomas, its role in tumorigenesis and invasion remains inconclusive." (PMID 39488665, 2024). "Two distinct subtypes of seminomas seem to exist according to their bearing of mutations in the KIT gene, in which the wild type seminomas have a higher level of methylation." (PMID 38791003, 2024). "Consistent with The Cancer Genome Atlas (TCGA) study of TGCT5, KIT driver mutations defined a subset of seminomas." (PMID 39461959, 2024). "Although KIT mutations appeared to be restricted to a subset of seminomas, amplifications spanning KIT were also observed in NSGCT." (PMID 39461959, 2024). "Multiple mutations affecting the same oncogene (KIT) were observed in only one participant with a clinical stage II seminoma." (PMID 39461959, 2024). "Mutations in the KIT gene were identified more frequently among seminomas when compared to non-seminomas, and more than one variant was observed in only one case." (PMID 37007070, 2023). "In seminoma, KIT mutation likely occurs pre-migration of PGC to the gonadal ridges, whereas these mutations arise post-migration in dysgerminoma." (PMID 37954076, 2023). "KIT mutation is more prevalent in seminomas, and it was the second most frequently mutated gene among our cases, with almost all cases being seminomas." (PMID 37007070, 2023). "Analysis comparing the mutational status of genes with clinicopathologic data revealed that KIT (p = 0.007) was significantly mutated in seminomas, and EGFR (p = 0.010) in stage IS." (PMID 37007070, 2023). "Further, KIT is mutated in about 25% of seminoma, and accounts for secondary mutations that confer resistance to drugs in other cancers." (PMID 35757413, 2022). "Similar c-kit mutations have been reported in dysgerminomas (the ovarian counterpart of seminomas), along with c-kit amplification associated with c-KIT protein overexpression evident through immunohistochemistry (IHC)." (PMID 35490363, 2022). "We demonstrate clear association in seminomas of CN-Sig-1 with KRAS/NRAS/KIT-mutation, a phenomenon also observed in HGSOC27." (PMID 32366847, 2020).
seminoma (continued). "Different from the germinomas in our cohort, most adult seminomas carried isochromosome 12p13, and some seminomas with isochromosome 12p retained activating KIT mutations, suggesting that the acquisition of isochromosome 12p precedes that of KIT mutations." (PMID 32999426, 2020). "Seminomas frequently exhibit an isochromosome of the short arm of chromosome 12 (isochromosome 12p) as well as mutations in KIT and RAS13." (PMID 32999426, 2020). "Association with seminoma was found for mutations in KIT, KRAS and NRAS and for putative oncogenic driver genes CBL, RAC1, PIK3CA, and CTNNB1 (analysed jointly due to lower frequency), p = 3.33 × 10−10, p = 1.41 × 10−6, p = 0.002, p = 0.009, respectively." (PMID 32366847, 2020). "Through adjusted analysis, we delineate independent association with seminoma histology for mutations in KIT, KRAS, NRAS and Pi3K/MTOR pathway gene sets and, independent of histology, association of KIT mutation with platinum sensitivity." (PMID 32366847, 2020). "The number of expressed CT genes was significantly higher in seminomas (P = 3.48 × 10−13) which were characterized by frequent mutations in driver genes (KIT, KRAS and NRAS)." (PMID 31070303, 2019). "The gene encodes the ligand for tyrosine-kinase KIT, which is commonly somatically mutated in seminomas." (PMID 30022029, 2018). "We showed that cryptorchidism was enriched in seminomas, especially in men with KIT-mutated seminomas, shedding new light on established cryptorchidism-TGCT associations that warrant further investigation." (PMID 29898407, 2018). "Integrative analysis identified numerous molecular features that distinguish each histology and reflect the histological composition of mixed tumors; it also identified molecularly defined subsets of seminomas associated with KIT mutations." (PMID 29898407, 2018). "Expression of 78 published immune gene expression signatures correlated with our DNA methylation-based lymphocyte content estimates and were highest in seminoma with KIT mutations compared to other samples." (PMID 29898407, 2018). "Within seminomas, KIT gene expression was higher in KIT-mutated tumors than in KIT-WT tumors, confirming the gain-of-function nature of these mutations (p = 0.001)." (PMID 29898407, 2018). "Of the six seminomas with mutations in both KIT and KRAS/NRAS, four were in men with a history of cryptorchidism (odds ratio = 7.3 [95% confidence interval 1.2–45.0]), all in the ipsilateral testicle." (PMID 29898407, 2018). "We also identified a subset of pure seminomas defined by KIT mutations, increased immune infiltration, globally demethylated DNA, and decreased KRAS copy number." (PMID 29898407, 2018). "KIT mutant multiplicities of an additional eight seminomas present a similar pattern, with variant allele fractions from DNA and RNA indicating a clonal nature." (PMID 29898407, 2018). "Genetic and protein analysis identified different gain-of-function mutations in the KIT gene (D816V, D816H) in seminomas, resulting in phosphorylation of KIT and PI3K and therefore constitutive activation of the PI3K pathway, even in the absence of KITLG." (PMID 25303610, 2015). "The depleted contribution of SBS1 in KIT-mutated seminomas could signal that these cells are, or were, maintained in prolonged mitotic arrest." (PMID 39461959, 2024). "CpGs islands tend to be fully demethylated in seminoma, predominantly in KIT/RAS mutated cases." (PMID 34680371, 2021). "In addition, seminomas can display genetic mutations in the KIT gene and they express the pluripotency marker POU5F1, which is not detectable in normal testis." (PMID 32176716, 2020). "KIT mutation status further separates seminomas into two groups." (PMID 29898407, 2018). "Globally demethylated genomes of KIT-mutated seminoma cells could provoke a similar immune response." (PMID 29898407, 2018).
seminoma (continued). "Activating KIT mutations may lock KIT mutant seminoma cells into a PGC-like state in which UHRF1 and DNMT1 expression are suppressed, preventing the development of NSGCT components, which appear to require DNA methylation capacity." (PMID 29898407, 2018). "Comparing the KIT mutational frequencies of exons 11, 13, 17 and 18 encoding different functional domains between germinomas, seminomas and gastrointestinal germ cell tumors (GISTs) showed strong similarities between seminomas and germinomas but a different distribution for GISTs." (PMID 27391150, 2016). "Unfortunately, although seminomas may harbour activating KIT mutations, responses in clinical studies of the KIT tyrosine kinase inhibitor imatinib mesylate have been disappointing, with no complete or even partial remissions." (PMID 25303610, 2015). "KIT mutations were observed predominantly in seminoma cases, as previously reported." (PMID 25609015, 2015). "This could suggest that KIT mutations occur after completion of PGC migration to the gonadal ridges in females, and may be in contrast to what has been suggested for males, where some reports have shown KIT mutations more frequently in bilateral seminomas." (PMID 17274819, 2007). "Alterations to the KIT‐KITLG pathway are often found in seminomas (up to 25%) and in mixed NSGCT with a seminoma component." (PMID 41384700, 2026). "As predicted from histological observations, transcripts encoding immune cell markers such as CD68, were generally higher in area 2 (ROIs 72–80), while the early germ cell and seminoma marker, KIT, was higher in section 1 (ROIs 81–91)." (PMID 40693358, 2026). "A recent analysis of the Cancer Genome Atlas demonstrated that KIT, KRAS, and NRAS gene variants were observed only in seminoma, while gene variants in B3GNT8, CAPN7, FAT4, GRK1, TACC2, and TRAM1L1 occurred only in embryonal carcinoma." (PMID 41426877, 2025). "One seminoma had a KRAS copy number variant, which co-existed with a KIT p.N822K missense mutation (TGCT-7)." (PMID 41009531, 2025). "Notable differences were observed through the assessment of primary and metastatic samples of seminoma, revealing BRD4 mutations were overrepresented in metastatic cases (p = 0.00125), while KIT mutations were more common in primary samples (p = 0.00191)." (PMID 41154418, 2025). "The singleton missense gain of function variant (p.E1051K) identified in PIK3CB was observed in two seminoma samples (TGCT-2 and TGCT-3), where it co-existed with either KIT (p.N822K) or KRAS (p.G12R) mutations." (PMID 41009531, 2025). "GCNS contains totipotent cells that can progress to seminoma or embryonal carcinoma, expressing markers such as KIT." (PMID 39001474, 2024). "c-KIT, which is normally expressed by germ cells, has been validated as a marker to distinguish seminoma from Sertoli cell tumors, as it is also expressed by undifferentiated neoplastic seminal cells." (PMID 38769240, 2024). "GCTs are also characterized by mutations in KIT, KRAS, and CDC27 genes, especially in seminomas, although their precise role is unclear." (PMID 39001474, 2024). "Seminomas with mutant KIT had significantly lower SBS1 than either wild-type seminomas (p = 0.0028) or NSGCT (p = 5.5 × 10−6)." (PMID 39461959, 2024). "Several genome wide studies has been conducted in GCTs: in 4–31% of seminomas, and up to 14% of non-seminomas, driver mutations were detected in three genes (KRAS, NRAS and KIT)." (PMID 36860862, 2023). "KRAS (STM: > 70%; GCT: 16%) and KIT (STM: 30%; GCT: 14%) were the most amplified or missense mutated genes in the GCT cohort with the majority being mutated in seminomas." (PMID 37726478, 2023). "Immunohistochemical staining reflects the shared genetic basis of the two cancers, and positive staining for OCT3/4 and SALL4 as well as strong membrane positivity for c-KIT (CD117) and D2-40 are used clinically to define both seminoma and dysgerminoma." (PMID 37954076, 2023).
seminoma (continued). "Alteration as mutations, copy number and expression of c‐KIT and c‐KIT‐PI3K pathway are significantly associated to seminoma." (PMID 33236849, 2021). "Specific somatic mutations or amplifications in tumor DNA have been identified in a few genes, but only KIT, KRAS, and NRAS have been implicated repeatedly in different studies, mostly in seminomas." (PMID 33805941, 2021). "KIT mutations are extremely rare in NS (2% of cases), while RAS mutations are present in a minority of cases with respect to seminoma." (PMID 34680371, 2021). "Meanwhile, compared to KIT/RAS mutated tumours, wildtype seminomas exhibit strong exposure of CN-Sig-6 (indicating focal amplification with high copy number states)." (PMID 32366847, 2020). "We noted several associations and confirmed previously reported characteristics, such as high KIT gene and protein expression in seminoma." (PMID 29898407, 2018). "Somatic mutation of only three genes achieved significance—KIT, KRAS, and NRAS—exclusively in samples with seminoma components." (PMID 29898407, 2018). "Seminomas with increased copies of KRAS (Chr 12) were more likely to have wild-type KIT (t test p = 0.0007)." (PMID 29898407, 2018). "CBL, which regulates ubiquitin-mediated degradation of KIT, was deleted in 48% of KIT-WT seminomas, leaving just one copy." (PMID 29898407, 2018). "Activin A bioactivity regulates synthesis of KIT and/or KITL, including in the testis, and hanging drop culture of testicular fragments in Activin A resulted in downregulation of both KIT mRNA and protein in a seminoma sample." (PMID 29250030, 2017). "Our result demonstrates that c-KIT is potently expressed and is potentially a specific tumor marker in equine seminoma, similar to human tumors." (PMID 27818621, 2016). "Although two of the seminomas showed immunohistochemical staining characteristics indicative of classical seminoma (PLAP+/c-KIT+), all 45 examined seminomas were morphologically consistent with spermatocytic seminoma." (PMID 22986090, 2012). "Next to mutations in c-KIT, amplification of chromosome 4q12, harboring the c-KIT gene, has been described in testicular GCC, likely related to the progression to seminoma." (PMID 22937135, 2012). "In a study of 20 canine seminomas, 100% (20/20) were found to be strongly positive for c-KIT, while 20% (4/20) were PLAP positive." (PMID 22986090, 2012). "In addition to the gain of chromosome 12p,25 which appears to confer pluripotency and invasiveness, somatic mutations in KIT, NRAS and KRAS genes and DNA hypomethylation are common features of seminomas." (PMID 40693358, 2026). "Furthermore, Cluster #2 was characterized by increased levels of the KIT oncogene protein, as it consisted of seminomas." (PMID 40011822, 2025). "While WGD was typically among the earliest events in TGCTs, a subset of seminomas (N=25, 17.4%) harbored driver mutations in KIT, KRAS, NRAS, or PIK3CA prior to WGD, irrespective of WGD timing." (PMID 40568177, 2025). "For example, KIT mutations, commonly found in seminomas, are relatively rare in non-seminomatous germ cell tumors, potentially affecting the effectiveness of targeted therapies." (PMID 40241724, 2025). "Among seminomas, tumors without i(12p) were significantly enriched for KIT mutations (Fisher’s exact test, P=2.27e-06)." (PMID 40568177, 2025). "Lack of KIT mutations were observed in all NSGCTs, including mixed TGCTs with seminoma components, indicating that only seminomas without KIT Proto-Oncogene mutations can acquire nonseminomatous histology." (PMID 40011822, 2025). "Mutations in KIT and RAS proto-oncogenes are identified in approximately 30% of dysgerminoma and seminoma with targeted sequencing revealing five mutations located in domains that are common to both seminoma and dysgerminoma." (PMID 37954076, 2023). "KIT, KARS and NRAS observed at very high mutation frequency were mainly occurred in seminoma." (PMID 36713456, 2022).
seminoma (continued). "So, although our main findings were not shared with public datasets (possibly due to population genomic differences), it is well known that for NS-TGCT, tumor-representative gene variants, such as KIT variants found only in seminomas, have not been found." (PMID 35565196, 2022). "Differences in somatic mutations between subtypes are also of concern, with our results suggesting that mutations in some genes (B3GNT8, CAPN7, FAT4, GRK1, TACC2, and TRAM1L1) occur only in embryonal carcinoma, while mutations in KIT, KARS, and NRAS are observed only in seminoma." (PMID 36713456, 2022). "As described in our results, mutation that only occurs in embryonal carcinoma (B3GNT8, CAPN7, FAT4, GRK1, TACC2 and TRAM1L1) or seminoma (KIT, KARS and NRAS) may be valuable molecular markers and therapeutic targets that need to be considered clinically." (PMID 36713456, 2022). "These tumours show a low rate of mutations compared to common cancers, which would make the prediction of mutations by AI more challenging, although somatic mutations of the KIT gene and its downstream mediators encoded by the KRAS and NRAS genes have shown significance in seminoma." (PMID 33809521, 2021). "Moreover, deletion of CBL (a negative regulator of KIT) can be recurrently found in KIT wild type seminomas." (PMID 34680371, 2021). "Gain-of function somatic mutations in KIT have been detected in up to 25% of seminomas but are very rare in non-seminoma germ cell tumors." (PMID 33805941, 2021). "Based on CNV and mutational status, two variants of seminomas do seem to exist, one with and one without KIT mutations, whereby the wild type variants do show a higher level of genome methylation." (PMID 31658757, 2019). "Compared to NSGCTs, even seminomas without a KIT mutation or KIT focal amplification had higher expression of KIT mRNA and protein." (PMID 29898407, 2018). "CBL copy number negatively correlated with KIT protein expression for most tumors; however, seminomas with KIT or KRAS mutations maintained high protein levels of KIT regardless of CBL copies, apparently escaping CBL regulation." (PMID 29898407, 2018). "Only by removing it were we able to reveal that seminomas lacked methylation genome wide and that those with KIT mutations had more complete lack of methylation." (PMID 29898407, 2018). "Previous studies noted both extensive lymphocytic infiltration and lack of DNA methylation in seminomas, features that we show for the first time to be more extreme in KIT-mutated seminomas." (PMID 29898407, 2018). "Gene signatures downstream of KIT signaling such as AKT, PI3K, KRAS, and JAK/STAT were high in seminomas, regardless of KIT or KRAS mutation status." (PMID 29898407, 2018). "After correction for lymphocytes, the remnant methylation is absent in a subgroup of seminomas that are highly enriched for KIT/KRAS mutations (p < 0.0001), suggesting an essentially complete lack of DNA methylation in this subset." (PMID 29898407, 2018). "The specific impact on KIT signaling in seminoma cells has yet to be addressed." (PMID 29250030, 2017). "Also, angioleiomyolipomas, small-cell lung carcinomas, seminomas/dysgerminomas, and leukemias frequently express c-KIT." (PMID 22839358, 2012). "Additionally, all KIT alterations were seen in seminomas only." (PMID 41009531, 2025). "On the other hand, even though both of patient SP2’s synchronous seminomas harbored KIT mutations, the methylation profile of his left-side seminoma more closely resembled that of patients SP23 and SP74’s right-side seminomas, which did not harbor any KIT mutation." (PMID 40358182, 2025). "In KIT/RAS wild type seminoma, a residual methylation could be detected." (PMID 34680371, 2021). "However, evidence for which RTKs contribute to TGCT behaviour, beyond KIT in seminomas, is limited." (PMID 29160922, 2018).